TTLL9 (tubulin tyrosine ligase like 9)
Description:
Probable tubulin polyglutamylase that generates side chains of glutamate on the gamma-carboxyl group of specific glutamate residues within the C-terminal tail of target proteins. Similar to TTLL1, may acquire enzymatic activity only in complex with other proteins as it is most likely lacking domains important for autonomous activity. Mediates tubulin polyglutamylation which induces establishment of microtubule heterogeneity in sperm flagella, thereby playing a role in normal motile flagella axoneme structure and sperm flagella beating pattern.
Synonyms: C20orf125; dJ310O13.1
Tractability: No criterion of Open Targets' tractability assessment is met for any kind of drug.
Gene: Protein-coding gene on chromosome 20 (31,870,634 to 31,945,000, forward strand). Ensembl gene ENSG00000131044.
Subcellular location: Cytoplasm, cytoskeleton, cilium basal body; Cytoplasm, cytoskeleton; Cytoplasm, cytoskeleton, flagellum axoneme
Subcellular location (Human Protein Atlas): End piece; Microtubules; Mid piece; Principal piece; Basal body; Mitotic spindle; Nucleoplasm; Primary cilium
Pathways (Reactome):
Metabolism of proteins: Carboxyterminal post-translational modifications of tubulin
Gene Ontology:
Molecular function: protein-glutamic acid ligase activity, elongating; tubulin binding; tubulin-glutamic acid ligase activity
Biological process: microtubule cytoskeleton organization
Cellular component: ciliary basal body; cytoskeleton
Genetic constraint (gnomAD): Loss-of-function variants: 41 observed, 57.57 expected, observed/expected ratio (o/e) 0.71, 90% interval 0.55 to 0.92. The upper end of that interval is the gene's LOEUF score, 0.92, which puts it in group 3 of 6, group 1 being the genes least tolerant of losing a copy. Missense variants: 467 observed, 530.4 expected, observed/expected ratio (o/e) 0.88, 90% interval 0.81 to 0.95. Synonymous variants: 158 observed, 193.06 expected, observed/expected ratio (o/e) 0.82, 90% interval 0.72 to 0.93.
Homologues: Orthologues: chimpanzee TTLL9 (99% identical), dog TTLL9 (89% identical), pig TTLL9 (89% identical), rat Ttll9 (88% identical), guinea pig TTLL9 (87% identical), mouse Ttll9 (86% identical), macaque TTLL9 (79% identical), tropical clawed frog ttll9 (69% identical), zebrafish ttll9 (68% identical), rabbit TTLL9 (49% identical), Caenorhabditis elegans ttll-9 (41% identical). Paralogues in human: TTLL1 (39% identical), TTLL6 (27% identical), TTLL13 (26% identical), TTLL4 (26% identical), TTLL2 (25% identical), TTLL7 (24% identical), TTLL11 (23% identical), TTLL3 (23% identical), TTLL10 (22% identical), TTLL8 (21% identical), TTLL12 (16% identical), KPRP (8% identical).
Diseases named in the same sentence as TTLL9 in open-access papers:
TTLL9 is named in the same sentence as 3 diseases in open-access papers, as found by Europe PMC text mining. Sharing a sentence is not in itself a finding about the gene and the disease. The quoted sentences say what the papers report.
male infertility (2 papers, 2020 to 2021). The inability of the male to effect fertilization of an ovum after a specified period of unprotected intercourse. "Studies using mouse models revealed that deletion of Ttll9, Vdac3, Dnah17, or Cfap97d1 resulted in the instability of sperm microtubule doublets 4–7, associated with sperm motility defects and male infertility." (PMID 34759295, 2021).
cancer (1 paper, 2022). A tumor composed of atypical neoplastic, often pleomorphic cells that invade other tissues. "Downregulation of Spink4 (its downregulation known to be associated with poor survival of cancer cells), Ttll9 (involved in microtubule cytoskeleton organization and protein polyglutamylation), and Nppa (has a role in mediating cardio-renal homeostasis) was also observed." (PMID 36130284, 2022).
TTLL9 also shares sentences with these, for which no sentence is quoted: Infertility (1 paper).